PLA2G4C (phospholipase A2 group IVC)
Description:
Calcium-independent phospholipase, lysophospholipase and O-acyltransferase involved in phospholipid remodeling with implications in endoplasmic reticulum membrane homeostasis and lipid droplet biogenesis. Preferentially hydrolyzes the ester bond of the fatty acyl group attached at the sn-2 position of phospholipids with choline and ethanolamine head groups, producing lysophospholipids that are used in deacylation-reacylation cycles. Transfers the sn-1 fatty acyl from one lysophospholipid molecule to the sn-2 position of another lysophospholipid to form diacyl, alkylacyl and alkenylacyl glycerophospholipids. Cleaves ester bonds but not alkyl or alkenyl ether bonds at sn-1 position of lysophospholipids. Catalyzes sn-2 fatty acyl transfer from phospholipids to the sn-2 position of 1-O-alkyl or 1-O-alkenyl lysophospholipids with lower efficiency. In response to dietary fatty acids, may play a role in the formation of nascent lipid droplets from the endoplasmic reticulum likely by regulating the phospholipid composition of these organelles. (Microbial infection) May play a role in replication and assembly of human hepatitis C virus (HCV). In response to HCV infection, promotes remodeling of host endoplasmic reticulum membranes to form organelle-like structures called membranous web, where HCV replication occur. Can further mediate translocation of replication complexes to lipid droplets to enable virion assembly. (Microbial infection) May facilitate human T-lymphotropic virus type 1 (HTLV-1) infection by promoting leukotriene B4 (LTB4) biosynthesis. LTB4 acts as a chemoattractant for HTLV-1-infected CD4-positive T cells and favors cell to cell viral transmission.
Synonyms: cPLA2-gamma
Tractability: Antibody: UniProt places it where antibodies can reach, with high confidence; its Gene Ontology location is reachable by antibodies, with medium confidence. PROTAC: its protein half-life has been measured; a small molecule that binds it is known.
Target class: Enzyme; Hydrolase
Gene: Protein-coding gene on chromosome 19 (48,047,843 to 48,110,850, reverse strand). Ensembl gene ENSG00000105499.
Subcellular location: Cell membrane; Endoplasmic reticulum membrane; Mitochondrion membrane; Lipid droplet
Subcellular location (Human Protein Atlas): Cytosol
Pathways (Reactome):
Metabolism: Acyl chain remodelling of PC; Acyl chain remodelling of PE; Acyl chain remodelling of PI; Hydrolysis of LPC; Hydrolysis of LPE
Gene Ontology:
Molecular function: acyltransferase activity, transferring groups other than amino-acyl groups; phosphatidylcholine lysophospholipase activity; phospholipase A2 activity; protein binding; calcium ion binding; calcium-dependent phospholipid binding; phospholipase A1 activity; phospholipid binding; phospholipase activity
Biological process: glycerophospholipid catabolic process; lipid droplet formation; phosphatidylcholine acyl-chain remodeling; phosphatidylethanolamine acyl-chain remodeling; platelet activating factor biosynthetic process; arachidonate metabolic process; inflammatory response; intracellular signal transduction; parturition; phospholipid metabolic process; glycerophospholipid metabolic process; phospholipid catabolic process
Cellular component: endoplasmic reticulum membrane; lipid droplet; mitochondrial membrane; plasma membrane; cytosol; membrane; nuclear envelope; nucleoplasm; cell cortex
Genetic constraint (gnomAD): Loss-of-function variants: 39 observed, 45.1 expected, observed/expected ratio (o/e) 0.86, 90% interval 0.67 to 1.13. The upper end of that interval is the gene's LOEUF score, 1.13, which puts it in group 4 of 6, group 1 being the genes least tolerant of losing a copy. Missense variants: 492 observed, 552.82 expected, observed/expected ratio (o/e) 0.89, 90% interval 0.83 to 0.96. Synonymous variants: 211 observed, 218 expected, observed/expected ratio (o/e) 0.97, 90% interval 0.86 to 1.09.
Homologues: Orthologues: chimpanzee PLA2G4C (99% identical), macaque PLA2G4C (89% identical), mouse Pla2g4c (57% identical), rat Pla2g4c (56% identical), zebrafish si:ch73-55i23.1 (30% identical), zebrafish pla2g4cl1 (29% identical), zebrafish pla2g4c (28% identical), zebrafish zgc:101699 (28% identical). Paralogues in human: PLA2G4F (28% identical), PLA2G4B (25% identical), PLA2G4D (25% identical), PLA2G4A (24% identical), PLA2G4E (23% identical).
Diseases named in the same sentence as PLA2G4C in open-access papers:
PLA2G4C is named in the same sentence as 22 diseases in open-access papers, as found by Europe PMC text mining. Sharing a sentence is not in itself a finding about the gene and the disease. The quoted sentences say what the papers report.
colon cancer (2 papers, 2017 to 2025). "The top downregulated genes included protease inhibitor Itih2, glycosyltransferase B3gnt5, as well as Eph receptor 6 (Ephb6) and phospholipase Pla2g4c, found to be overexpressed in a colon cancer cell line and human colon cancer tissues." (PMID 40631899, 2025). "PLA2G4C plays the prognostic role in breast and colon cancer." (PMID 28749961, 2017).
colorectal cancer (2 papers, 2017 to 2019). A primary or metastatic malignant neoplasm that affects the colon or rectum. "To further check the role of PRKACB, MECOM, PLA2G4C, FGF2 and FGF in colorectal cancer, we further analyzed the genes involved in the MAPK pathway for their association with patient’s survival using the survExpress online tool." (PMID 28749961, 2017). "SNP in genes, such as PPP1R15A, PLA2G4C, CMTM8, and IFNL3, are responsible for the growth of various cancers, such as colorectal cancer, osteosarcoma, and hepatocellular carcinoma, but SNP in these genes may be associated with the pathogenesis of BRCA." (PMID 31311202, 2019).
allergic asthma (1 paper, 2018). A asthma with a basis in a pathological type I hypersensitivity reaction. "It is thus possible that increased expression of Pla2g4c is a ubiquitous event in the airways of allergic asthma." (PMID 30161143, 2018).
allergic bronchopulmonary aspergillosis (1 paper, 2025). Allergic bronchopulmonary aspergillosis (ABPA) is a rare immunologic pulmonary disorder caused by hypersensitivity to Aspergillus fumigatus, clinically manifesting with poorly controlled asthma and recurrent pulmonary infiltrates. "Studies have found high expression of Pla2g4c, Pla2g2c, Pla2g2d, and Pla2g5 in a mouse model of ABPA (allergic bronchopulmonary aspergillosis)." (PMID 40278587, 2025).
asthma (1 paper, 2018). "The results might be consistent with previous report where an increase in the expression of Pla2g4c was demonstrated in lungs of a murine asthma model induced by Aspergillus fumigatus." (PMID 30161143, 2018).
atherosclerosis (1 paper, 2007). A disease characterized by the build-up of fatty material and calcium deposition in the arterial wall resulting in partial or complete occlusion of the arterial lumen. "Moreover genes encoding for a variety of proteins that have been associated with atherosclerosis were up-regulated including phospholipase A2 (PLA2G4C), prostaglandin synthase 2 (PTGS2) also known as cyclooxygenase-2, thrombin receptor like-1 and the gene encoding for superoxide dismutase 2 (SOD2)." (PMID 17534423, 2007).
behavioral disorders (1 paper, 2025). "Notably, genes associated with immune modulation and inflammation (e.g., Dusp1, Lrrc39, E2f2), neuroplasticity and memory (e.g., Cpeb3, Efnb3), and behavioral disorders (e.g., Pla2g4c) exhibited substantial changes." (PMID 40285614, 2025).
breast carcinoma (1 paper, 2023). "PLA2G4C was downregulated in the tested TNBC cell lines, and higher PLA2G4C mRNA levels correlated with longer survival in breast cancer patients." (PMID 38017485, 2023).
fatty liver disease (1 paper, 2020). A reversible condition wherein large vacuoles of triglyceride fat accumulate in liver cells via the process of steatosis. "Importantly, PLA2G4C knockdown hampers LD formation upon HCV stimulation, while PLA2G4C overexpression leads to LD formation in hepatocytes and enhances LD accumulation in the liver of mice fed a high-fat diet, suggesting its potential role in fatty liver disease." (PMID 33086624, 2020).
lung carcinoma (1 paper, 2023). "Targeting the Lands Cycle through lysophosphatidylcholine acyltransferase 3 (LPCAT3) or phospholipase A2 group IVC (PLA2G4C) inhibition resulted in increased ferroptosis, indicating that proper functioning of the Lands Cycle is necessary to prevent cell death in KRAS-mutant lung cancer." (PMID 37779896, 2023).
Obesity (1 paper, 2023). Accumulation of substantial excess body fat. "PLA2G4C abundance was lower in male placentas and LPCAT4 abundance was lower solely in females in obesity." (PMID 37770949, 2023).
cancer (4 papers, 2013 to 2023). A tumor composed of atypical neoplastic, often pleomorphic cells that invade other tissues. "Changes in cPLA2γ/PLA2G4C expression in GBM tumors could be a hallmark of cancer." (PMID 36765904, 2023). "In the case of ovarian cells, PLA2G4A as well as PLA2G4C were lower in cancer cell lines compared to normal." (PMID 23626839, 2013). "According to a pan-cancer analysis based on the GEPIA, cPLA2γ/PLA2G4C expression is downregulated in nine types of tumors but not in GBM or lower grade gliomas, whereas it is upregulated in seven types of tumors." (PMID 36765904, 2023).
infection (3 papers, 2017 to 2022). The state of being infected such as from the introduction of a foreign agent such as serum, vaccine, antigenic substance or organism. "Only 2 genes were shared in every comparison when treatment was constant and infection status was compared: those encoding keratin 13 (Krt13) and cytosolic phospholipase A2 gamma (Pla2g4c)." (PMID 34928716, 2022). "Several genes were significantly upregulated (Pla2g4a, Pla2g4c, Pla2g7, Ptgs1, Ptgs2, Pla1, Tbxas1) or downregulated (Alox5, Pla2g2d, Pla2g1b, Pla2g4b, Pla2g4f) during infection." (PMID 35812400, 2022).
mental illness (1 paper, 2022). "One previous study confirmed that another three family members, PLA2G4A, PLA2G4B, and PLA2G4C, are strongly associated with mental illness in the Chinese population." (PMID 36056316, 2022).
respiratory diseases (1 paper, 2020). "The top ten genes (Clca1, Chil4, Itln1, Tff1, Muc5ac, Clca3b, Chodl, Pla2g4c, Mmp10, and Stac2) with the highest fold change are involved in various inflammatory responses and respiratory diseases." (PMID 33066398, 2020).
tumor (1 paper, 2017). "In conclusion, targeting the MAPK signal transduction pathway through the targeting of FGF9, FGF2, MECOM, PRKACB and PLA2G4C might increase tumor responsiveness to irinotecan and improve patient survival thus being therapeutically and prognostic significant in CRC patients." (PMID 28749961, 2017). "Targeting the MAPK signal transduction pathway through the targeting of the FGF2, FGF9, MECOM, PLA2G4C and PRKACB might increase tumor responsiveness to irinotecan treatment." (PMID 28749961, 2017).
PLA2G4C also shares sentences with these, for which no sentence is quoted: glioma (1 paper); hepatocellular carcinoma (1); metabolic syndrome (1); osteosarcoma (1); ovarian carcinoma (1); pancreatic cancer (1).